VWCE (von Willebrand factor C and EGF domains)
Description:
May be a regulatory element in the beta-catenin signaling pathway and a target for chemoprevention of hapatocellular carcinoma.
Synonyms: URG11; FLJ32009; VWC1
Tractability: Antibody: UniProt places it where antibodies can reach, with high confidence; UniProt predicts a signal peptide or a membrane-spanning region; its Gene Ontology location is reachable by antibodies, with medium confidence.
Gene: Protein-coding gene on chromosome 11 (61,255,672 to 61,295,334, reverse strand). Ensembl gene ENSG00000167992.
Subcellular location: Secreted
Subcellular location (Human Protein Atlas): Nucleoplasm; Cytosol; Vesicles; Predicted to be secreted
Gene Ontology:
Molecular function: protein binding; calcium ion binding
Biological process: cellular response to virus
Cellular component: cytoplasm; cytosol; nucleoplasm; extracellular region
Genetic constraint (gnomAD): Loss-of-function variants: 66 observed, 99.91 expected, observed/expected ratio (o/e) 0.66, 90% interval 0.54 to 0.81. The upper end of that interval is the gene's LOEUF score, 0.81, which puts it in group 3 of 6, group 1 being the genes least tolerant of losing a copy. Missense variants: 1,137 observed, 1,200 expected, observed/expected ratio (o/e) 0.95, 90% interval 0.9 to 1. Synonymous variants: 497 observed, 489.21 expected, observed/expected ratio (o/e) 1.02, 90% interval 0.94 to 1.09.
Homologues: Orthologues: chimpanzee VWCE (99% identical), macaque VWCE (96% identical), pig VWCE (84% identical), rabbit VWCE (77% identical), mouse Vwce (76% identical), dog VWCE (75% identical), rat Vwce (75% identical), tropical clawed frog vwce (45% identical). Paralogues in human: MUC5AC (24% identical), MUC5B (23% identical), OTOG (22% identical), FCGBP (21% identical), VWF (21% identical), OTOGL (20% identical), MUC6 (18% identical), KCP (18% identical), MUC2 (18% identical), MUC19 (17% identical), TECTA (17% identical), ZAN (17% identical), and 7 more.
Diseases named in the same sentence as VWCE in open-access papers:
VWCE is named in the same sentence as 17 diseases in open-access papers, as found by Europe PMC text mining. Sharing a sentence is not in itself a finding about the gene and the disease. The quoted sentences say what the papers report.
breast carcinoma (5 papers, 2018 to 2025). "In our study, VWCE expression was associated with a better prognosis and was immune infiltration in breast cancer." (PMID 34020650, 2021). "Using cell culture and animal models, the functional characterization of the role of VWCE revealed that the loss of its expression is an important event in the progression of breast cancer." (PMID 33194737, 2020). "For the first time, we have fully revealed the potential role of VWCE in breast cancer progression, and found that VWCE is associated with the inhibition of breast cancer metastasis (e.g., tumor cell growth, migration, invasion, and epithelial-interstitial transformation [EMT])." (PMID 33194737, 2020). "Therefore, we hypothesized that VWCE expression is associated with immune infiltration in breast cancer, and is a potential marker of the tumor immune microenvironment." (PMID 34020650, 2021). "VWCE has been reported to function as a tumor suppressor in breast cancer via the induction of WDR1 expression." (PMID 38123554, 2023). "Information in the TIMER database uncovered that mRNA expression of VWCE was fundamentally lower in breast cancer tissues when compared with normal tissues (p < 0.01)." (PMID 34020650, 2021). "The results showed that the expression of VWCE mRNA in breast cancer tissue was significantly lower than that in normal tissues." (PMID 34020650, 2021). "This means that the role of VWCE in breast cancer is different from that of other inflammation-related tumors." (PMID 33194737, 2020). "We also used the TCGA datasets to examine the level of VWCE mRNA expression in 1,079 human breast cancer specimens relative to the 113 normal breast tissues." (PMID 33194737, 2020). "The overexpression of VWCE inhibited the proliferation, migration, invasion, and chemoresistance of the breast cancer cell lines." (PMID 33194737, 2020). "In order to examine the level of VWCE protein expression in human breast cancer, we performed an immunohistochemical analysis of the purchased tissue microarray, which consisted of 87 breast cancer tissues and 87matched normal breast tissue samples." (PMID 33194737, 2020). "We next examined the level of VWCE protein expression in breast cancer cell lines and tumor tissues, which was consistent with our VWCE mRNA expression data." (PMID 33194737, 2020). "In conclusion, this study found that VWCE is a potent tumor suppressor in breast cancer, and its growth inhibition is mediated in part by the expression of its downstream target gene, WDR1." (PMID 33194737, 2020). "In this study, the expression and function of VWCE in breast cancer cells are studied, and the possible anti-tumor mechanisms are further explored." (PMID 33194737, 2020). "We first analyzed the level of VWCE expression in breast cancer tissues and cultured the breast cancer cell lines using qRT-PCR, immunohistochemistry, and Western blot." (PMID 33194737, 2020). "We found that VWCE expression was downregulated in breast cancer cells and tissues compared to normal breast epithelial cells or the adjacent normal tissues." (PMID 33194737, 2020). "To investigate the function of VWCE in breast cancer, we first transfected the MDA-MB-231 and MDA-MB-453 cell lines using a control and VWCE expression vector, and verified VWCE expression by Western blot and qRT-PCR." (PMID 33194737, 2020). "In the current study, we have demonstrated for the first time, that VWCE is down-regulated in breast cancer and inhibits the proliferation, migration, invasion and metastasis of breast cancer cells both in vitro and in vivo." (PMID 33194737, 2020). "The main hypothesis we can draw from this study is that an increased level of VWCE as a regulator of WDR1 may represent a therapeutic strategy for breast cancer; however, this attractive assumption requires further validation in animal models." (PMID 33194737, 2020). "In the present study, we sought to elucidate the role of VWCE in breast cancer metastasis." (PMID 33194737, 2020).
breast carcinoma (continued). "Notably, VWCE overexpression inhibited the proliferation and metastasis of mouse breast cancer cells, suggesting that VWCE is a potential therapeutic target for breast cancer." (PMID 33194737, 2020). "Recently, the upregulation of VWCE has been found in prostate cancer; however, its biological role in breast cancer remains unknown." (PMID 33194737, 2020). "Therefore, VWCE may represent a novel tumor suppressor, for which its deregulation promotes breast cancer progression via the upregulation of WDR1." (PMID 33194737, 2020). "Similarly, using qRT-PCR, we assessed the level of VWCE mRNA expression in 50 human breast cancer specimens relative to 50 normal breast tissue samples, and VWCE mRNA is highly expressed in normal tissues adjacent to the tumor; However, in contrast, the expression in breast cancer tissue is lower." (PMID 33194737, 2020). "Thus, our findings suggest that VWCE may be a novel tumor suppressor that limits breast cancer progression by regulating WDR1 expression." (PMID 33194737, 2020). "We selected two breast cancer cell lines that represent the mesenchymal phenotype, MDA-MB-231 and MDA-MB-435 cells, to elucidate the mechanism by which VWCE mediates its anticancer effects." (PMID 33194737, 2020). "Von Willebrand factor C and EGF domain (VWCE) is a member of the Von Willebrand factor (VWF) gene family; however, its function, regulatory mechanism, and clinical value in breast cancer remain unclear." (PMID 33194737, 2020). "The level of VWCE mRNA expression in breast cancer tissues and matched adjacent non-cancerous tissues (n = 50) was assessed by qRT-PCR analysis." (PMID 33194737, 2020).
hepatocellular carcinoma (3 papers, 2018 to 2020). A malignant tumor that arises from hepatocytes. "Up-regulation of the VWCE gene (synonym URG11) was demonstrated to promote proliferation, migration, and invasion in the prostate, non-small cell lung, and hepatocellular carcinomas." (PMID 33348918, 2020). "For example, VWCE has been found to be highly expressed in hepatocellular carcinoma, gastric cancer, pancreatic cancer, and lung cancer, and is associated with increased invasion and metastasis of these tumor cells." (PMID 33194737, 2020).
prostate carcinoma (3 papers, 2018 to 2023). A carcinoma that arises from epithelial cells of the prostate gland. "Collectively, these data suggested that the lower expression level of VWCE is associated with prostate cancer development." (PMID 38123554, 2023). "Overexpression of VWCE in prostate cancer cells inhibits mTORC1 activation, anchorage-independent cell growth, and tumor development in nude mice." (PMID 38123554, 2023). "More importantly, overexpression of VWCE inhibited the colony formation ability of prostate cancer cells." (PMID 38123554, 2023). "Here, the authors identify VWCE as a negative regulator of amino acid-dependent mTORC1 signaling and a potential as a therapeutic target in prostate cancer treatments." (PMID 38123554, 2023). "Consistent with the TCGA expression database, analysis based on the Cancer Cell Line Encyclopedia (CCLE) also indicates that the expression level of VWCE is much higher in the liver cancer cell lines HepG2 and Huh7 compared with the prostate cancer cell lines PC3, 22Rv1, and DU145." (PMID 38123554, 2023). "More importantly, overexpression of VWCE inhibits the development of prostate cancer." (PMID 38123554, 2023). "Overexpression of VWCE inhibited the xenograft tumor growth of these prostate cancer cells." (PMID 38123554, 2023). "We reveal that VWCE acts as a tumor suppressor in prostate cancer by inhibiting the mTORC1 pathway." (PMID 38123554, 2023). "Bioinformatics analyses indicate a downregulation of VWCE in prostate cancer tissues." (PMID 38123554, 2023). "Bioinformatic analysis reveals that expression of VWCE is reduced in prostate cancer." (PMID 38123554, 2023). "Importantly, overexpression of VWCE impairs prostate cancer progression." (PMID 38123554, 2023). "Therefore, VWCE may serve as a potential therapeutic target for the treatment of prostate cancers." (PMID 38123554, 2023). "Overexpression of VWCE suppressed amino acid-stimulated mTORC1 activation in prostate cancer cell lines, but not liver cancer cell lines." (PMID 38123554, 2023).
liver cancer (2 papers, 2023). An epithelial or non-epithelial malignant neoplasm that arises from the liver. "In contrast, the proliferation of liver cancer cells was not affected by VWCE overexpression." (PMID 38123554, 2023).
lupus erythematosus (1 paper, 2025). An autoimmune, connective tissue chronic inflammatory disorder affecting the skin, joints, kidneys, lungs, heart, and the peripheral blood cells. "For instance, FAM71E1 and EMC10 have been associated with lupus erythematosus and genes like PGA3, VWCE, and PTOV1 are associated with immune infiltrates and immunity in various tumors." (PMID 41009814, 2025).
uterine cancer (1 paper, 2024). Primary or metastatic malignant neoplasm involving the uterine corpus and/or the cervix. "VWCE and CLDN15 have previously been associated with various neoplasms; however, their role in uterine cancers remains largely undescribed." (PMID 38540371, 2024). "The DIANA-Tarbase documents these miRNAs as regulators of VWCE and ADCYAP1R1, respectively, potentially reinforcing the involvement of these genes in uterine cancer." (PMID 38540371, 2024).
tumor (8 papers, 2012 to 2024). "This suggests that VWCE may activate or inhibit immune cells infiltrating the tumor, although the underlying mechanism involved is unknown." (PMID 34020650, 2021). "These indicating that VWCE may acts as a tumor suppressor in vivo, supporting a role for VWCE in the regulation of tumor growth via its effects on cellular proliferation." (PMID 33194737, 2020). "We further analysed the methylation status of VWCE, TSPAN9 and ADAM12 genes in 45 adjacent-to-tumour tissues." (PMID 32019179, 2020). "We observed that TSPAN9 and ADAM12, but not VWCE, protein levels were significantly higher in tumours than in non-neoplastic tissues (p < 0.05)." (PMID 32019179, 2020). "A study focused on uncovering clinically significant aberrantly methylated genes in tumor cells reported three genes to be exclusively hypomethylated in TNBC, specifically Von Willebrand factor C and Epidermal Growth Factor domain-containing protein (VWCE), tetraspanin-9 (TSPAN9), and ADAM12." (PMID 38473804, 2024). "In addition, VWCE promotes tumor cell migration and invasion through EMT, as VWCE overexpression leads to decreased levels of N-cadherin, vimentin, and the EMT-induced transcription factor, ZEB1, as well as elevated E-cadherin levels, indicating a significant inhibition of EMT processes." (PMID 33194737, 2020).
cancer (5 papers, 2018 to 2023). A tumor composed of atypical neoplastic, often pleomorphic cells that invade other tissues. "First, the VWCE (Von Willenbrand factor C and Epidermal Growth Factor domain-containing protein) gene encodes a protein that is overexpressed in many cancer tissues and cell lines, and that promotes cancer development and progression." (PMID 32019179, 2020). "The level of VWCE mRNA expression was lower in moderately invasive cells (MCF-7 and BT474) than in non-tumorigenic MCF-10A cells, and was the lowest in highly invasive cancer cell lines (MDA-MB-453, SKBR-3, and MDA-MB-231), as assessed by reverse transcription-PCR." (PMID 33194737, 2020). "VWCE overexpression significantly inhibited the proliferation of MDA-MB-453 and MDA-MB-231 cells compared with the negative control groups (p < 0.05), as determined by a cancer cell colony formation assay." (PMID 33194737, 2020).
VWCE also shares sentences with these, for which no sentence is quoted: benign prostatic hyperplasia (1 paper); breast tumors (1); Cirrhosis (1); colon cancers (1); esophageal cancer (1); gastric cancer (1); lung carcinoma (1); oral cancer (1); pancreatic cancer (1).